ITIH5 (inter-alpha-trypsin inhibitor heavy chain 5)
Description:
May act as a tumor suppressor.
Synonyms: ITI-HC5; PP14776; MGC10848
Gene: Protein-coding gene on chromosome 10 (7,559,270 to 7,667,021, reverse strand). Ensembl gene ENSG00000123243.
Subcellular location: Secreted
Subcellular location (Human Protein Atlas): Golgi apparatus; Vesicles; Predicted to be secreted
Genetic constraint (gnomAD): Loss-of-function variants: 42 observed, 56.23 expected, observed/expected ratio (o/e) 0.75, 90% interval 0.58 to 0.97. The upper end of that interval is the gene's LOEUF score, 0.97, which puts it in group 4 of 6, group 1 being the genes least tolerant of losing a copy. Missense variants: 999 observed, 1,052.8 expected, observed/expected ratio (o/e) 0.95, 90% interval 0.9 to 1. Synonymous variants: 456 observed, 440.54 expected, observed/expected ratio (o/e) 1.04, 90% interval 0.96 to 1.12.
Homologues: Orthologues: macaque ITIH5 (97% identical), chimpanzee ITIH5 (96% identical), rabbit ITIH5 (87% identical), guinea pig ITIH5 (81% identical), pig ITIH5 (80% identical), mouse Itih5 (78% identical), rat Itih5 (78% identical), dog ITIH5 (73% identical), tropical clawed frog itih5 (56% identical), zebrafish itih5 (49% identical). Paralogues in human: ITIH6 (35% identical), ITIH3 (32% identical), ITIH2 (31% identical), ITIH1 (29% identical), ITIH4 (29% identical), PARP4 (15% identical), VWA5B1 (14% identical), VWA3B (13% identical), VWA3A (13% identical), VWA5A (12% identical), VWA5B2 (12% identical).
Diseases named in the same sentence as ITIH5 in open-access papers:
ITIH5 is named in the same sentence as 50 diseases in open-access papers, as found by Europe PMC text mining. Sharing a sentence is not in itself a finding about the gene and the disease. The quoted sentences say what the papers report.
breast carcinoma (22 papers, 2008 to 2024). "For example, ITIH5 has been reported to be significantly down-regulated and hyper-methylated in breast cancer (BC), and high ITIH5 expression was associated with favorable outcomes in BC patients." (PMID 33744857, 2021). "In the presented study, we observed abundant loss of ITIH5 expression in the basal-type subgroup of bladder cancer similar to our findings in breast cancer." (PMID 33924987, 2021). "By comparison of breast cancer with healthy control samples, a prevalent loss of ITIH5 expression was found in primary breast tumors (median fold-change (FC): 18-fold downregulation)." (PMID 28231808, 2017). "Previously, we identified aberrant ITIH5 promoter hypermethylation as the molecular cause for its gene inactivation in breast cancer, which was associated with unfavorable prognosis." (PMID 28231808, 2017). "The ECM-modulator inter- α-trypsin inhibitor heavy chain family member five (ITIH5) was recently identified as tumor suppressor potentially involved in impairing breast cancer progression but molecular mechanisms underlying its function are still elusive." (PMID 28231808, 2017). "Underlying mechanisms of the epigenetic shift induced by ITIH5 in basal-type breast cancer cells and the putative role of specific ECM components and receptors appear complex, and must be addressed in future studies." (PMID 28231808, 2017). "ITIH5 loss was pronounced in breast cancer subtypes with unfavorable prognosis like basal-type tumors." (PMID 28231808, 2017). "Previously, we revealed that loss of ITIH5 expression caused by aberrant promoter hypermethylation is associated with poor prognosis and clinical correlates of metastasis in breast cancer." (PMID 28231808, 2017). "In tumor development, downregulation of ITIH5 caused by aberrant DNA hypermethylation has been reported in breast cancer, bladder cancer, colon cancer, gastric cancer and lung cancer." (PMID 28231808, 2017). "Hypermethylation in the upstream region of the promoter-associated CpG island of ITIH5, has been detected in breast cancer, and associated with adverse clinical outcome, suggesting ITIH5 as a potential prognostic marker." (PMID 23285140, 2012). "ITIH5 downregulation in breast cancer, caused by promoter hypermethylation, is associated with poorer clinical outcome, and reduced protein expression was proved to be a bad prognostic marker in invasive node-negative patients." (PMID 19809427, 2009). "Applying gene set enrichment analyses (gene ontology (GO)), we revealed ITIH5 associated up- or down-regulation of genes involved in extracellular matrix organization which is in line with previous reports and findings in basal-type breast cancer cells." (PMID 33924987, 2021). "Moreover, ITIH5 was causative for an epigenomic reprogramming of basal-type breast cancer cells upon a shift from mesenchymal to an epithelial-like phenotype while suppressing lung metastases formation in vivo." (PMID 33924987, 2021). "As DAPK1 (death-associated protein kinase (DAP Kinase)) is a well-known tumor suppressor, we aimed to demonstrate whether its re-expression may explain some of the ITIH5-associated suppressive attributes in basal-type breast cancer cells." (PMID 28231808, 2017). "Interestingly, in aggressive mammary cancer cells, ITIH5 triggered an epigenetic reprogramming which was associated with a demethylation of various promoter regions, including that of DAPK1, a tumor suppressor gene and putative blood-based biomarker in several tumor entities." (PMID 32046186, 2020). "ITIH5 has been identified as an epigenetically silenced (class II) tumor suppressor gene (which we abbreviate as C2TSG) in breast cancer and multiple other tumor entities—for example, bladder and colon cancer." (PMID 39518085, 2024). "In this study, we present in vivo data indicating that ITIH5 can also locally and strongly suppress tumor growth in breast cancer." (PMID 35158755, 2022).
breast carcinoma (continued). "Here, we show that ITIH5 overexpression in MDA-MB-231 breast cancer cells can also locally suppress tumor growth by 85%, when transplanted into the mammary fat pad of nude mice." (PMID 35158755, 2022). "E.g., ITIH5 is a hyaluronan binding extracellular matrix protein that has been found to confer metastasis suppressive functions in both breast cancer and pancreatic cancer." (PMID 36139547, 2022). "In highly invasive human breast cancer cells of the triple negative phenotype (TNBC), ITIH5 expression triggered an epigenetic reprogramming associated with a shift in cell differentiation, which effectively suppressed the growth of metastases in vivo." (PMID 35158755, 2022). "For example, ITIH5 suppressed breast cancer metastasis and induced cell death by regulating TGF-β superfamily signalling switches, and elevated the expression of the tumour-suppressor gene DAPK1 by modulating epigenetic reprogramming." (PMID 33935281, 2021). "The tumor suppressor protein ITIH5 has been reported to be down-regulated in many cancer entities, e.g., breast cancer, colon cancer, lung cancer, cervical cancer, gastric cancer, pancreatic cancer and bladder cancer." (PMID 33924987, 2021). "rs17142881 is in the inter-alpha-trypsin inhibitor heavy chain family member 5 (ITIH5) gene, which acts as a tumor suppressor in breast cancer cell lines through epigenetic reprogramming and as a metastasis suppressor in breast and pancreatic cancers." (PMID 34437536, 2021). "In breast cancer, ITIH5 modulates the TGF-β signaling cascade via the co-receptor endoglin which impairs metastases promoters’ like ID1." (PMID 33924987, 2021). "In 2008, ITIH5 was described to be epigenetically silenced in breast cancer and five years later ITIH5 DNA methylation has been identified as a putative blood-based biomarker for the early detection of breast cancer." (PMID 32046186, 2020). "ITIH5 (inter-α-trypsin inhibitor heavy chain 5) has been identified as a novel prognostic marker for breast cancer, mediated by promoter hypermethylation, and is a novel candidate tumor suppressor gene in colon cancer." (PMID 32849837, 2020). "In the plasma cohort, on basis of SPAG6, PER1 and ITIH5, sensitivity for breast cancer detection was 64%." (PMID 31741713, 2019). "ITIH5 showed significant increases in methylation level for breast cancer patients (4.49% versus 5.93%, p = 0.0085) and DCIS patients (4.49% versus 6.87%, p < 0.0001)." (PMID 31741713, 2019). "In the present study we give clear evidence that the ECM modulator ITIH5 is involved in controlling breast cancer cell migration and colonization in vitro and in vivo." (PMID 28231808, 2017). "In contrast, ITIH5-expressing MDA-MB-231 cells grew in a monolayer with a cuboidal single-cell shape indicating a profound impact of ITIH5 action in this metastatic breast cancer cell line." (PMID 28231808, 2017). "Facing the identified phenotype switch of aggressive breast cancer cells driven by ITIH5 expression, we focused on potential mechanisms." (PMID 28231808, 2017). "Our results provide evidence that ITIH5 triggers a reprogramming of breast cancer cells with known stem CSC properties towards an epithelial-like phenotype through global epigenetic changes effecting known tumor suppressor genes like DAPK1." (PMID 28231808, 2017). "Addressing the role of ITIH5 in breast cancer, two different in vitro tumor models were generated reflecting both the luminal and basal subtype." (PMID 28231808, 2017). "The potential biomarkers DKK3 and ITIH5 seem to be more breast cancer specific (94% to 99%) but less sensitive (14% to 33%) in both the test and the validation sets." (PMID 23320751, 2013). "ITIH5 was methylated in seven (5.2%) of 135 healthy controls, in one (2.6%) of 39 benign controls, and 19 (13.8%) of 138 breast cancer samples." (PMID 23320751, 2013).
breast carcinoma (continued). "Our next goal is to discover and characterize more potential biomarkers for early breast cancer detection with a quality comparable to that of ITIH5 and DKK3 promoter methylation." (PMID 23320751, 2013). "Promoter methylation of the DKK3/ITIH5 gene combination allowed significant discrimination of breast cancer sera from various control conditions." (PMID 23320751, 2013). "However, in ITIH5-deficient malignant cells such as wild-type MDA-MB-231 or T47D, reflecting distinct molecular breast cancer subtypes (basal (TNBC) and luminal), ITIH5681aa suppressed cell and colony growth in vitro." (PMID 35158755, 2022). "Performing functional drug-response analyses in vitro using (aggressive) breast cancer cells upon treatment with the two different recombinant ITIH5 derived polypeptides, we confirmed mimicry of tumor cell growth inhibition mediated by the recombinant VIT protein only." (PMID 36139547, 2022). "In breast cancer, we demonstrated the ITIH5-mediated suppression of metastasis growth in vivo." (PMID 35158755, 2022). "Since we demonstrated a significant role of ITIH5 on basal-type breast cancer cells, we here assessed ITIH5 mRNA expression according to the sub-classification of high-grade bladder that has previously been shown to reflect hallmarks of breast cancer biology." (PMID 33924987, 2021). "Basal-like breast cancers frequently show low methylation levels of tumor suppressor genes, single CpGs of SPAG6, PER1, NKX2-6 and ITIH5 however showed a higher methylation frequency in this molecular breast cancer subtype (59%, 42%, 52% and 41%, respectively)." (PMID 31741713, 2019). "To give insight into ITIH5 biology going beyond the assumed role as a prognostic biomarker in breast carcinomas, we established two different stable gain-of-function models, i.e. weak-aggressive T47D and metastatic MDA-MB-231 single-cell clones overexpressing full-length ITIH5." (PMID 28231808, 2017). "In the current study, ITIH5 downregulation was abundantly found in distant metastases and intrinsic subtypes associated with poor prognosis, i.e. luminal B, HER2-enriched and basal-like breast cancer." (PMID 28231808, 2017). "The combination of DKK3 and ITIH5 methylation revealed a sensitivity of 39.9% (55 of 138) for the detection of breast cancer and a specificity of 93.3% (126 of 135) and of 97.4% (38 of 39) in healthy controls and benign disease controls (P < 0.0001), respectively." (PMID 23320751, 2013). "Additionally, DKK3 and ITIH5 specificity in colon cancer cfDNA is much higher in comparison to RASSF1A, indicating the eligibility of DKK3 and ITIH5 as potential breast cancer biomarkers." (PMID 23320751, 2013). "We hypothesize that DKK3 and ITIH5 may be valuable biomarkers for the blood-based detection of breast cancer in patients with dense breast tissue because of their high specificity in the control specimens." (PMID 23320751, 2013). "In addition, ITIH5 may act as a metastasis suppressor gene in several tumor entities; this property has been best studied in pancreatic cancer and breast cancer." (PMID 39518085, 2024). "In addition, overexpression of ITIH5 inhibited the invasive growth pattern of aggressive MDA-MB-231 breast cancer cells and modulated the expression of genes known to be involved in metastasis, including ENG, which led to a switch in TGF-β superfamily signalling." (PMID 33935281, 2021). "Therewith, ITIH5 may represent an ECM modulator in epithelial breast tissue mediating suppression of tumor initiating cancer cell characteristics which are thought being responsible for the metastasis of breast cancer." (PMID 28231808, 2017). "However, a significant downregulation of ITIH5 expression (52%) was observed in breast cancer only." (PMID 18226209, 2008). "Although ITIH5 is upregulated in the tumor, it retains its tumor-suppressive function in CCA, similar to other tumor entities such as breast cancer and pancreatic cancer, where it is downregulated." (PMID 39518085, 2024).
breast carcinoma (continued). "ITIH5 is a member of inter‐alpha‐trypsin inhibitor (ITI) family, which functions as a tumour suppressor in breast cancer and thyroid cancer." (PMID 35194950, 2022). "These previous findings supported our notion that ITIH5 modulates mechanotransductive downstream signaling affecting ECM-cell interactions and finally, migration behavior of breast cancer cells." (PMID 33924987, 2021). "In 2017, we firstly presented data proposing involvement of ITIH5 in ECM remodeling, affecting the ECM-cell interaction in MDA-MB-231 breast cancer cells." (PMID 33924987, 2021). "Although liquid biopsy remains challenging, a combination of SPAG6, NKX2-6, ITIH5 and PER1 (SNiPER) provides a promising tool for blood-based breast cancer detection." (PMID 31741713, 2019). "The sensitivity and specificity achieved using ITIH5, DKK3 and RASSF1A promoter methylation to distinguish between women with breast cancer and healthy controls was 67 and 69%, respectively, with the 95% confidence interval for the AUC being [0.63, 0.76]." (PMID 29301500, 2018). "Overall, CST6, HOXB4, ITIH5 and RASSF1 were more frequently methylated in CTCs from breast cancer patients compared to MNCs from healthy controls." (PMID 29190932, 2017). "Therefore, we initially aimed to decipher ITIH5 hypermethylation and its subtype specific expression in a large dataset of The Cancer Genome Atlas (TCGA), in total comprising 1095 different breast cancer samples, 113 normal breast tissues and 7 distant metastases derived from primary breast tumors." (PMID 28231808, 2017). "In the current study, we provide evidence that the ECM modulator ITIH5 suppresses tumor cell migration and colonization of metastatic MDA-MB-231 breast cancer." (PMID 28231808, 2017). "In summary, the three-marker panel with ITIH5, DKK3, and RASSF1A exhibits significantly increased levels of methylation in serum cfDNA from breast cancer patients compared with both age-matched healthy women and women with a benign breast disease." (PMID 23320751, 2013). "In the present study, seven potential breast cancer marker candidates (SFRP1, SFRP2, SFRP5, WIF1, DKK3, ITIH5, and RASSF1A) were studied with regard to early breast cancer detection in serum." (PMID 23320751, 2013). "We initially assessed promoter methylation of SFRP1, SFRP2, SFRP5, ITIH5, DKK3, and WIF1 in 112 paired breast cancer tissue and serum samples by using qualitative MSP." (PMID 23320751, 2013). "In addition, and similarly to breast cancer, ITIH5 may prove to be a useful prognostic marker." (PMID 19809427, 2009). "ITIH5 was included on basis of previous work, where we showed that a panel of ITIH5 and DKK3 could detect breast cancer with 41% sensitivity." (PMID 31741713, 2019). "Therefore, markers were tested in a plasma cohort, achieving a 64% sensitivity for breast cancer detection using SPAG6, PER1 and ITIH5." (PMID 31741713, 2019). "Tumor-specific methylation of the three-gene panel (ITIH5, DKK3, and RASSF1A) might be a valuable biomarker for the early detection of breast cancer." (PMID 23320751, 2013). "Therefore, we constructed a xenograft mouse tumorigenesis model through orthotopic transplantation of human breast cancer cells either overexpressing ITIH5 (ΔpBK-ITIH5 clone #12) or lacking ITIH5 expression (ΔpBK-mock clone #1) into the mammary fat pad of BALB/cnu/nu mice." (PMID 35158755, 2022). "However, increases in SPAG6, PER1, NKX2-6 and ITIH5 promoter methylation may not be confined to breast cancer and therefore needs to be tested in non-breast cancer patients such as colorectal- and lung cancer patients, the second and third most common cancers in women." (PMID 31741713, 2019). "Breast cancer patients showed a non-significant higher methylation frequency for SPAG6 (mean of 6.6% in benign controls versus 8.4% in breast cancer cases, p = 0.2536), PER1 (2.6% versus 4.8%, p = 0.5792), NKX2-6 (1.3% versus 2.9%, p = 0.1898) and ITIH5 (6.8% versus 5.9%, p = 0.9343)." (PMID 31741713, 2019).